GLRA1 (glycine receptor alpha 1)
Diseases named in the same sentence as GLRA1 in open-access papers:
GLRA1 is named in the same sentence as 31 diseases in open-access papers, as found by Europe PMC text mining. Sharing a sentence is not in itself a finding about the gene and the disease. The quoted sentences say what the papers report.
hyperekplexia (30 papers, 2012 to 2026). "The Y303C mutation in the GLRA1 gene is a well-identified cause of startle syndrome or hyperekplexia, where the EC50 for glycine spikes 70-folds and maximal currents decrease 50-folds." (PMID 41129221, 2025). "Mutations in GPHN and GLRA1 (Glycine receptor alpha 1) have been linked to hyperekplexia in humans, a disorder that manifests from childhood and is characterized by exaggerated startle responses, stiffness, and an inability to move." (PMID 39068495, 2024). "In the Miniature Australian Shepherd with clinical signs resembling hyperekplexia, the causal variant pinpointed a 36-bp deletion spanning the exon–intron boundary in the glycine receptor alpha 1 (GLRA1) gene." (PMID 38003185, 2023). "To summarize, this study describes a novel canine GLRA1 variant causing clinical signs similar to human hereditary hyperekplexia." (PMID 37222814, 2023). "Variants in GLRA1 are known to cause hereditary hyperekplexia in humans; however, this is the first study to associate a variant in canine GLRA1 with the disorder, establishing a spontaneous large animal disease model for the human condition." (PMID 37222814, 2023). "A well stablished example of the pathological GlyR relevance is human hyperekplexia, a neuromotor disorder frequently associated with genetic alterations in the genes encoding α1 and β GlyRs (Glra1 and Glrb)." (PMID 35401105, 2022). "It has been reported from humans carrying a GLRA1 mutation and thus suffering from hyperekplexia that the affected patients are anxious to fall upon exposure to unexpected noise or tactile stimuli." (PMID 32848605, 2020). "Her diagnosis was confirmed as hereditary hyperekplexia with GlRA1 hybrid gene mutations based on the sequencing results." (PMID 32332682, 2020). "Hyperekplexia is a rare hereditary neurological disorder; only 5 glycine receptor alpha 1 subunit gene (GLRA1) mutations have been reported in 5 Chinese patients." (PMID 32332682, 2020). "Spasmodic is a mouse line carrying a spontaneous mutation A52S in the Glra1 gene resulting in hyperekplexia due to lower affinity to the agonist glycine." (PMID 32848605, 2020). "Although the diagnosis of Hyperekplexia is based on clinical findings, pathogenic variants in five genes have been reported to cause Hyperekplexia, of which GLRA1 accounts for about 80% of cases." (PMID 30866851, 2019). "Dominant and recessive mutations have been identified in GLRA1 gene as pathogenic variants in many individuals with the familial form of Hyperekplexia and occasionally in simplex cases." (PMID 30866851, 2019). "Some recessive mutations can induce hyperekplexia in combination with other recessive GLRA1 mutations." (PMID 28985719, 2017). "In our patient, after the GLRA1 mutations were identified and hyperekplexia was diagnosed, CZP administration was initiated at 0.02 mg/kg per day, administered in 3 doses, with slight increases every 3 day." (PMID 28985719, 2017). "Our findings contribute to a growing list GLRA1 mutations associated with hyperekplexia and provide new insights into correlations between phenotype and GLRA1 mutations." (PMID 28985719, 2017). "Here we report a case of genetically confirmed hyperekplexia caused by two novel GLRA1 mutations, which together constitute a compound mutation, that were inherited from the proband’s unaffected parents." (PMID 28985719, 2017). "Hyperekplexia results from mutations in GLRA1 and GLRB encoding the human glycine receptor and also the glycine transporter SLCA5." (PMID 26968164, 2016). "Mutations in the glycine receptor alpha 1 subunit gene occur in about 30 percent of hyperekplexia cases." (PMID 24969041, 2014). "Shiang and colleagues were first to show that hyperekplexia is caused by hereditary mutations in the GLRA1 gene that encodes the α1 subunit of the inhibitory human glycine receptor (hGlyR) chloride channel." (PMID 24405574, 2014). "Recently, the GLRA1 V170S mutation was shown to produce an autosomal dominant form of hyperekplexia." (PMID 24405574, 2014).
hyperekplexia (continued). "A heterozygous missense mutation (c.211A/T, p.Ile71Phe) was detected in our patient in exon 3 of the GLRA1 gene, establishing the diagnosis of hyperekplexia 1 and suggesting that the mutation is an autosomal dominant form of the disease." (PMID 24969041, 2014). "Mutations in GLRA1, encoding the GlyR α1 subunit, are the major genetic cause of startle disease/hyperekplexia in humans and cause similar disorders in mice and Poll Hereford cattle." (PMID 23238346, 2013). "A point mutation in the murine Glra1 locus, which selectively suppresses Zn potentiation, generates a phenotype that mimics that of patients with hyperekplexia (hereditary startle disease) and thus is indicative of decreased glycinergic inhibition." (PMID 22791190, 2012). "Notably, GLRA1 stands out as the predominant pathogenic gene in hereditary hyperekplexia, the presence of exaggerated head retraction reflexes in response to nose tapping signals an exaggeration in brain stem reflexes, offering a crucial diagnostic clue." (PMID 38975479, 2024). "The GLRA1 gene encodes a glycine receptor subunit, which mediates postsynaptic inhibition in the central nervous system and the variants in the gene are known to cause hereditary hyperekplexia in humans (OMIM 138491, phenotype MIM number 149400)." (PMID 37222814, 2023). "Therefore, her diagnosis was finally confirmed as hereditary hyperekplexia with GlRA1 hybrid gene mutations based on the sequencing results." (PMID 32332682, 2020). "In the case of P4, clonazepam that was found to be effective in patients with the same GLRA1 variant related to hyperekplexia could be administered to our patient." (PMID 32695065, 2020). "Diseases associated with GLRA1 include hyperekplexia, which induce severe stiffness." (PMID 31969651, 2020). "We documented abnormal behaviors and motor activities during NREM and REM sleep, with objective improvement with clonazepam, in two siblings affected with hereditary hyperekplexia caused by a novel splice mutation affecting the consensus splice acceptor site of intron 2 of the GLRA1 gene." (PMID 31392847, 2019). "Indeed, one third of the patients with hyperekplexia carry a loss-of-function mutation in the alpha 1 subunit (GLRA1) of the glycine receptor and such a genetic condition has not been previously modeled in zebrafish." (PMID 31048868, 2019). "In conclusion, we reported abnormal behaviors and motor activities during NREM and REM sleep in two siblings affected with hereditary hyperekplexia caused by a mutation in the GLRA1 gene, with the majority of motor defects being successfully treated by clonazepam." (PMID 31392847, 2019). "Therapeutic management in hyperekplexia might include medication with an allosteric potentiator of the inhibitory GABAA receptor clonazepam in patients with variants in GLRA1 and SLC6A5." (PMID 31604777, 2019). "We next reviewed reported GLRA1 mutations in hyperekplexia according to mutation location." (PMID 28985719, 2017). "Previously, it has been shown that mutations in the α1 subunit of glycine receptor (GLRA1) are responsible for the neurological disorder hyperekplexia (MIM 149400) characterized by muscle rigidity originating from the CNS as well as an exaggerated startle response." (PMID 27506666, 2016). "In part, this may be historical: GLRA1 was the first startle disease gene to be discovered in 1993 and mutations in this gene explain the majority of cases of dominant hyperekplexia." (PMID 23238346, 2013). "In addition to mutations in the genes GLRB (encodes glycine receptor β-subunit), SLC6A5 (encodes glycine transporter 2) and GPHN (encodes the integral membrane protein gephyrin), mutations in the gene GLRA1 (encodes the α1-subunit of the GlyR) account for 40 - 80% of hyperekplexia." (PMID 23006332, 2012).
hyperekplexia (continued). "Numerous studies investigating disturbances in glycinergic inhibition rely on mutations within the receptor genes GLRA1 and GLRB which have been associated with startle disease (hyperekplexia) derogating the nerve-muscle circuit." (PMID 32848605, 2020). "Hyperekplexia patients with a benign phenotype and variants in SLC6A5 are significantly less likely to have recurrent infantile apnea than those with GLRA1 variants." (PMID 31604777, 2019). "Patients diagnosed with startle disease/hyperekplexia do not always carry mutations in the known associated disease genes (GLRA1, GLRB, SLC6A5)." (PMID 37903619, 2023). "Eight mutations have been detected with GLRA1 genes, and 20% of the patients with a GLRA1 mutation had no family history of hyperekplexia." (PMID 32332682, 2020). "Interestingly, although Glra1-/- mice depict motor dysfunction reminiscent to hyperekplexia, Glra2-/- and Glra3-/- do not depict motor impairment." (PMID 31048868, 2019).
startle disease (16 papers, 2011 to 2025). "Startle disease is a rare disorder associated with mutations in GLRA1 and GLRB, encoding glycine receptor (GlyR) α1 and β subunits, which enable fast synaptic inhibitory transmission in the spinal cord and brainstem." (PMID 34630038, 2021). "We report sleep phenotypes and polysomnographic findings in two siblings with a novel homozygous variant of the GLRA1 gene causing hereditary hyperekplexia (HH)." (PMID 31392847, 2019). "The neurological disorder startle disease is caused by glycinergic dysfunction mainly due to missense mutations in genes encoding GlyR subunits (GLRA1 and GLRB)." (PMID 30186111, 2018). "Mutations associated with startle disease are distributed across the overall GlyR sequence and have been identified in the GlyR α1 and β subunits (encoded by genes GLRA1 and GLRB)." (PMID 30186111, 2018). "GLRA1 (the only gene in the 20th region) mediates postsynaptic inhibition in the central nervous system, and mutations have been associated with startle disease." (PMID 26943675, 2016). "Mutations in the GlyR α1 subunit gene GLRA1 are the most common cause for the rare neuromotor disorder hyperekplexia (Stiff baby syndrome, Startle disease, OMIM 149100)." (PMID 26733802, 2015). "In this manuscript, we present the clinical and genetic investigations of a Hungarian family affected by hyperekplexia 1 and the identification of a novel disease-causing heterozygote missense mutation of the GLRA1 gene." (PMID 24969041, 2014). "Of the clinical laboratories world-wide offering screening for startle disease, seven screen for GLRA1 mutations, three offer screening for GLRB and only one offers screening for SLC6A5 mutations." (PMID 23238346, 2013). "A point mutation at the murine Glra1 locus, which selectively suppresses Zn potentiation, generates a phenotype that mimics that of patients with hereditary startle disease and thus is indicative of decreased glycinergic inhibition." (PMID 22918698, 2012). "The primary cause of startle disease is defective inhibitory glycinergic transmission due to missense, nonsense, or frameshift mutations in the glycine receptor (GlyR) α1 gene (GLRA1), although large deletions of exons 1–7 have also been reported." (PMID 21420493, 2011). "The main cause of startle disease in humans are mutations in the GLRA1 gene." (PMID 37963764, 2024). "GLRA1 encoding GlyRα1 is the most commonly affected gene underlying startle disease in humans." (PMID 37963764, 2024). "However, many mutations in the GlyR α1 subunit gene (GLRA1) that cause startle disease show dominant inheritance." (PMID 28588452, 2017). "Mutations in the genes GLRA1 (GlyRα1), GLRB (GlyRβ), and SLC6A5 encoding GlyT2 are the major underlying causes of startle disease in humans and rodents." (PMID 37963764, 2024). "To unravel the fate of the GlyRβ subunit and a possible role in the pathophysiology of startle disease, we crossed Glrbeos/eos animals (with normal GlyRα1 expression) with Glra1 mutant mouse strains." (PMID 37963764, 2024). "Here, we used knock-in mice expressing endogenous mEos4b-tagged GlyRβ that were crossed with mouse Glra1 startle disease mutants." (PMID 37963764, 2024). "The study establishes a natural large animal model for human GLRA1-related hereditary hyperekplexia." (PMID 37222814, 2023). "Mutations in the glycine receptor alpha 1 subunit gene (GLRA1) result in hyperekplexia 1 (OMIM149400) and occur in about 30 percent of hyperekplexia 1 cases." (PMID 24969041, 2014). "The karyotype found hyperekplexia 1, with alteration in the GLRA1 gene, position chr5:151." (PMID 40136121, 2025). "Within our patient cohort several patients diagnosed for startle disease do not carry a mutation in the known common genes, i.e., GLRA1, GLRB, SLC6A5." (PMID 37903619, 2023). "Individuals with startle disease lacking mutations in GLRA1 and SLC6A5 were screened for genetic variation in GLRB coding exons and donor and acceptor splice junctions by Sanger DNA sequencing." (PMID 23238346, 2013).
startle disease (continued). "Therefore, a genetic test was conducted, and at eleven months old, the patient was diagnosed with hyperekplexia 1, with changes in the GLRA1 gene, position chr5:151,859,888, C>T variation, where aspartate was replaced in codon 125 by asparagine, causing a genetic alteration." (PMID 40136121, 2025). "Mutations in the genes encoding this GlyR subtype (GLRA1 and GLRB) cause startle disease, characterized by noise- or touch-induced non-epileptic seizures, excessive muscle stiffness and neonatal apnea episodes in cattle, mice and humans." (PMID 28588452, 2017).
Anxiety (2 papers, 2020 to 2024). Intense feelings of nervousness, tension, or panic often arise in response to interpersonal stresses. "Here, we compared two mouse models harboring either a mutation in the murine Glra1 or Glrb gene with regard to anxiety and startle phenotypes." (PMID 32848605, 2020). "The present study investigated spastic mice carrying a Glrb mutation and spasmodic mice with a Glra1 mutation to study anxiety- and fear-related behavior in rodents." (PMID 32848605, 2020). "In contrast, altered anxiety-related behavior characterized by massively increased startle reactivity was identified in spasmodic mice that carry a Glra1 missense mutation A52S leading to functional changes in glycine affinity but no alteration in GlyRβ expression." (PMID 37963764, 2024). "To study if the Glra1 gene has an impact on anxiety-related behavior, we used homozygous spasmodic mice." (PMID 32848605, 2020). "Thus, a mutation in the Glra1 gene had no impact on anxiety-related behavior at least not in the open field test investigated here." (PMID 32848605, 2020).
schizophrenia (2 papers, 2020 to 2025). A major psychotic disorder characterized by abnormalities in the perception or expression of reality. "Among possible targets of these eRNA candidates are ARHGEF38 and SH3YL1, which have been linked to bipolar disorder and suicide, GLRA1 and MCTP2 were found to be associated with schizophrenia, and CHIR-B3, MHCIA7, MHCIY as well as MICA are genes involved in the immune system." (PMID 32854615, 2020).
agoraphobia (1 paper, 2020). An anxiety disorder characterized by an intense, irrational fear of venturing out into open places or situations in which help (or escape) might not be available should excessive anxiety or panic symptoms develop. "Possibly, in human additional changes in fear and fear-related circuits either due to gene-gene interactions e.g., with GLRA1 genes or epigenetic factors are necessary to create the agoraphobia and in particular the startle phenotype." (PMID 32848605, 2020).
autism (1 paper, 2023). Persistent deficits in social interaction and communication and interaction as well as a markedly restricted repertoire of activity and interest as well as repetitive patterns of behavior. "(S) Log-normalized counts of transcripts for the autism-related transcription factor Auts2 and several neurotransmitter receptor and ion channel genes whose expression changes across postnatal development (Glra1, Grin2b, Kcnj3, and Kcnq3)." (PMID 36876911, 2023).
bone fracture (1 paper, 2020). "Furthermore, we discovered that two genes coding for the GABA receptors GABBR2 and GLRA1 and the gene coding for glutamate decarboxylase GAD1, showed an association with total body BMD, and remarkably GABBR2 associated with bone fractures." (PMID 31969651, 2020).
developmental delay (1 paper, 2019). "Moreover, patients with variants in GLRB and SLC6A5 are more likely to have a developmental delay than those with GLRA1 variants." (PMID 31604777, 2019).
Epileptic encephalopathy (1 paper, 2020). A condition in which epileptiform abnormalities are believed to contribute to the progressive disturbance in cerebral function. "ZDHHC9, ITPR1, and GLRA1 showed meaningful variants in the gene panel for neurodevelopment disorders during reanalysis but were not actually included in the gene panel for epileptic encephalopathy." (PMID 32695065, 2020).
optic neuritis (1 paper, 2017). Optic neuritis is inflammation of the optic nerve, the nerve that carries the visual signal from the eye to the brain.The conditionmay cause sudden, reduced vision in the affected eye(s). "The frequency of AQP4, glycine receptor alpha 1 subunit, and MOG antibodies was determined in a cohort of patients with isolated optic neuritis; the combination was found in 45% (23 of 51) of the cases of the cases and was associated with unilateral or bilateral, severe or recurrent optic neuritis." (PMID 29064441, 2017).
Tinnitus (1 paper, 2024). Tinnitus is an auditory perception that can be described as the experience of sound, in the ear or in the head, in the absence of external acoustic stimulation. "The most downregulated genes in the tinnitus (when compared to the non-tinnitus group) were LOC103690064, AABR07048397.1, Trpv1, AABR07061378.1, Ncaph, Spata20, Rps19, Enpp3, Grtp1, and Glra1." (PMID 38562529, 2024).
tumor (3 papers, 2021 to 2022). "In summary, our analysis indicates, on one side, that the concentration of GLRA1-3 mutations across TM1 and TM2 is very likely not random, and, on the other, that these changes certainly disrupt the GlyR function in the tumor cells carrying them, as seen for HPX." (PMID 35836931, 2022).
overlap syndrome (1 paper, 2023). "However, excluding an incidental overlap syndrome requires investigation of further dogs affected by GLRA1 mutation." (PMID 37222814, 2023).
GLRA1 also shares sentences with these, for which no sentence is quoted: neurological disorder (5 papers); Apnea (2); diabetes (2); epilepsy (2); bipolar disorder (1); cancer (1); Cognitive impairment (1); Dravet syndrome (1); familial hemiplegic migraine (1); female infertility (1); genetic disorders (1); glaucoma (1); hyperkinesias (1); movement disorder (1); myopia (1); Parasomnia (1); Umbilical hernia (1); viral infection (1).